SIRPA (signal regulatory protein alpha)
Diseases named in the same sentence as SIRPA in open-access papers (continued):
Sharing a sentence is not in itself a finding about the gene and the disease.
cancer (continued). "CD47/SIRPα crosstalk has been conceptually chosen to develop NPs that could efficiently block cancer resistance to macrophage-mediated phagocytosis." (PMID 34575416, 2021). "Therefore, macrophage checkpoints including CD47–signal regulatory protein-alpha (SIRPA) signaling are considered to play important roles in cancer surveillance." (PMID 33799989, 2021). "Owing to decorating with Sirpα variants, engineered exosomes could target CD47-overexpressing cancer cells, regulate macrophage phagocytosis through disruption of CD47-Sirpα interaction and lead to innate and adaptive immune responses against cancer." (PMID 34576180, 2021). "Therefore, blockage of the CD47/SIRPα axis is a successful strategy to target and limit cancer cells." (PMID 34093795, 2021). "Interestingly, the addition of anti-CD47 Ab or Sirpα-ex fusion protein enabled WT BMDMs to phagocytize cancer cells, but to a significantly lesser degree than Sirpα−/− BMDMs under the same stimulation." (PMID 34050181, 2021). "We firstly discovered that an FDA-approved anti-hypotensive drug azelnidipine could be repositioned for cancer immunotherapy by dual targeting SIRPα and PVR through docking-based virtual screening." (PMID 34068552, 2021). "Finally, therapeutic interest in the CD47/SIRPα axis has grown tremendously in recent years following the discovery that many cancers co-opt CD47 expression to evade antitumor immunity." (PMID 34197341, 2021). "Many studies have reported that tumors evade macrophage phagocytosis and immune surveillance by activating the inhibitory signal via the ligation of SIRPα (which is expressed on phagocytes as a receptor) with CD47 (which is highly expressed on cancer cells as a ligand)." (PMID 34349643, 2021). "Moreover, there was genetic variation of human neutrophil Fcγ receptors and SIRPα in antibody-dependent cellular cytotoxicity toward cancer cells." (PMID 34285919, 2021). "However, there has been limited information about the function of SIRPα+ DCs and their roles in cancer immunotherapy." (PMID 31996683, 2020). "Antibodies blocking the interaction between CD47 and its receptor on macrophages, signal regulatory protein alpha (SIRPα), have been shown to diminish the inhibitory signaling transduced to macrophages via the CD47-SIRPα axis, thus enabling the phagocytosis of cancer cells." (PMID 33603751, 2020). "CD47 blocking agents, such as monoclonal antibodies targeting CD47/SIRPα, could interrupt the interaction between cancer cells and macrophages and induce phagocytosis, potentially providing an effective method of cancer therapy." (PMID 33469516, 2020). "Some studies have shown how CD47 expression is upregulated in cancer cells, whereas the regulatory mechanism underlying Sirpα expression in TAMs is still not clear." (PMID 32296015, 2020). "Notably, we found that the co-cultures were already sufficient to trigger a decrease in macrophage SIRPα, and an increase in cancer cells CD47." (PMID 32231135, 2020). "Thus, the CD47:SIRPα axis is referred to as an innate immune checkpoint and is being targeted in a number of clinical trials in various cancer types including AML, breast cancer, CLL, lymphoma and head neck skin cancer." (PMID 33552071, 2020). "In summary, these results demonstrated that CD47/SIRPα blocking peptides, pep-20 and its derivate, could serve as promising candidates to promote macrophages-mediated phagocytosis and immune response in cancer immunotherapy." (PMID 33020240, 2020). "Lactate, which is highly produced by a vast number of cancers, might induce Ap-2α activity and subsequently promote Elk-1 and Sirpα expression in TAMs." (PMID 32296015, 2020). "The proteolysis-resistant analog pep-20-D12 could serve as a potential candidate for cancer immunotherapy by blocking CD47/SIRPα, especially in combination with RT to elicit synergistic effects." (PMID 33020240, 2020). "The CD47/SIRPα axis was also identified as an immune checkpoint inhibitor in cancer therapy." (PMID 32984001, 2020).
cancer (continued). "Thus, targeting SIRPα with hAB21 is a promising therapeutic approach to treat human cancers by reprogramming innate immunity to sensitize cancers to immunotherapy." (PMID 33256806, 2020). "In human CRC patient samples, we confirmed that the Elk-1 protein could bind to the Sirpα DNA promoter in TAMs and that carcinomas could potentiate this effect." (PMID 32296015, 2020). "Cancer cells expressing high levels of CD47 could activate SIRPα and inhibit macrophage-mediated destruction." (PMID 31575023, 2019). "The expression of MUC16 and SIRPA was barely detectable in the cancer adjacent normal tissues." (PMID 28383029, 2017). "Antibodies or other blocking agents targeting CD47/SIRPα could block communication between cancer cells and macrophages and induce phagocytosis, potentially an effective method of cancer therapy." (PMID 27863402, 2016). "NF-κB is considered as important transcription factor in macrophages linking inflammation and cancer, the study explored whether NF-κB could affect the expression of SIRPα and the polarization of macrophages." (PMID 27793032, 2016). "CD47 enabled the cancer cell to evade immune-surveillance and attack by sending “don't eat me” signal to phagocytic cells, such as macrophages and dendritic cells (DCs), via binding SIRPα, which prevents phagocytosis and T cell activation." (PMID 27863402, 2016). "Multiple strategies had been developed for cancer therapy by targeting CD47/SIRPα interaction." (PMID 27863402, 2016). "Here, we demonstrated that SIRPA-knockout (KO) iPSC-derived macrophages (iMacs) exhibit superior antitumor activity against various CD47-expressing tumors in vitro when combined with cancer-targeted monoclonal antibodies (mAbs) or chimeric antigen receptors (CARs)." (PMID 42291136, 2026). "Thus, understanding how SIRPα is regulated at the post-translational level provides valuable insight into its context-dependent function and offers new strategies to fine-tune immune responses against cancer." (PMID 41486149, 2026). "From the perspective of the “Cancer Cell Fusion” theory, a possible explanation for the favourable outcomes of CD47-SIRPα blockade is that CD47 on cancer cells may act as a trigger for macrophage-cancer cell fusion, mediated by the SIRPα marker on myeloid cells." (PMID 39967663, 2025). "Anti-CD47 antibodies that block the interaction of CD47 with its ligand SIRPα, expressed on macrophages, have shown promising activity in preclinical cancer models by triggering cancer cell phagocytosis and enhancing adaptive immune responses against the cancer cells." (PMID 38690738, 2024). "Therefore, the CD47/SIRPA axis might also represent an interesting therapeutic candidate for these cancers." (PMID 36442992, 2023). "Therefore, a potential ideal approach for cancer immunotherapy could involve inhibiting the interaction between SIRPα and CD47 while maintaining the binding between SIRPγ and CD47." (PMID 38125492, 2023). "In addition to serving as therapeutic target, SIRPα also represents a biomarker, which can be used to stratify patients by myeloid cell expression patterns and to track the migration and dynamics of myeloid cells in the context of cancer." (PMID 38164132, 2023). "Recently, pharmaceutical communities have shifted their attention to the development of new anti-cancer medicines that target innate immunity checkpoints, such as the immune checkpoint of macrophages: a cluster of differentiation (CD) 47/signal regulatory protein alpha (SIRPα) pathway." (PMID 36726125, 2023). "Furthermore, recent studies have revealed that the combination of anti-PD1/PD-L1 and inhibition of CD47/SIRPα signaling developed more effective cancer immunotherapy through activating macrophages phagocytosis and antitumor effects which can further activate CD8+ T cells." (PMID 36845095, 2023). "Thus, SIRPα is both a potential therapeutic target, and a potential biomarker in cancer." (PMID 35883493, 2022).
cancer (continued). "Hence, by counteracting signaling cascades involved in pro-inflammatory responses, SIRPα may play a key role in modifying macrophage polarization in cancer in addition to its role as phagocytosis inhibitor." (PMID 36325334, 2022). "The new information brought by our work describing the role of NADPH oxidase activation during ADCC by PMN and its regulation by SIRPα might help to design new agents to enhance myeloid cell function in the treatment of cancer while limiting adverse effects on healthy cells." (PMID 35795660, 2022). "Furthermore, SIRPα-EVs treatment promoted dense infiltration of T cells in a syngeneic cancer mouse model, raising the possibility that CD47-targeted therapy could unleash innate and adaptive antitumor responses." (PMID 36297672, 2022). "Thus, targeting the CD47-SIRPα axis, either through the CD47 or SIRPα blockade, may also promote antigen-presenting cell function, and stimulate T cell-mediated anti-cancer immunity." (PMID 34944850, 2021). "Taken together, CD47 gene expressions are regulated by multiple transcription factors, which could be transcriptional modification by pyroglutamate formation that enhances the binding of CD47 to SIRPα, consequently, inhibits phagocytosis by phagocytes and promotes cancer cell immune escape." (PMID 34512146, 2021). "In addition to antibodies, the SIRPα/CD47 axis can be blocked by the use of recombinant SIRPα protein, whereby the exogenously added SIRPα protein interacts with endogenous CD47 on cancer cells, thereby preventing interaction with endogenous SIRPα expressed on phagocytes." (PMID 33105656, 2020). "Disruption of the CD47/SIRPα axis with specific mAbs may promote cancer cell elimination by macrophages, and it is a potential immunotherapeutic strategy recently described for different cancers, including SCLC and NSCLC." (PMID 32082304, 2019). "High-dimensional cytometry confirmed discrete, cancer-enriched myeloid clusters expressing CD47, SIRPα, PD-L1, CD73, and Galectin-9." (PMID 41683933, 2026). "In various malignant tumors, inhibiting the interaction between CD47 and SIRPα has been demonstrated to boost the phagocytosis of cancer cells by macrophages, promoting their clearance." (PMID 40385528, 2025). "The myeloid-specific immune checkpoint regulator SIRPα is a receptor for CD47, which is expressed on both tumors and normal tissues and represents a promising target for cancer immunotherapy." (PMID 40136470, 2025). "In many cancer types, CD47, which binds to signal-regulatory protein alpha (SIRPα), initiates inhibitory signaling pathways that prevent malignant cells from being phagocytosed by macrophages." (PMID 40356928, 2025). "Another notable finding was the significant expression of SIRPA, an inhibitory receptor on macrophages, and its ligand CD47, which is often overexpressed in cancers." (PMID 40788962, 2025). "The SIRPα/CD47 axis serves as a critical immune checkpoint, inhibiting macrophage-mediated phagocytosis of cancer cells." (PMID 40136470, 2025). "The future unfolds with the promise of transformative breakthroughs in cancer therapeutics, propelled by our ongoing exploration of the intricate interplay between CD47 and SIRPα." (PMID 39040441, 2024). "Furthermore, the dual blockade of CD47/SIRPα and PD-1/PD-L1 signaling, which respectively suppress innate and adaptive immune responses, has shown enhanced therapeutic efficacy in various cancer types, providing a promising avenue for cancer treatment that stimulates both arms of the immune system." (PMID 38475778, 2024). "The ligand of SIRPA is CD47, which is known as a “don’t eat me” signal and is highly expressed on cancer cells compared with normal cells." (PMID 38920727, 2024). "Presently, clinical trials involving the anti-SIRPα monoclonal antibody BI 770371, evorpacept, and the SIRPα-4-1BBL fusion protein DSP107, among many others, are underway across various other cancer types." (PMID 38342925, 2024).
cancer (continued). "The pseudotime trajectory analysis showed a similar SIRPα expression in the macrophages and an increase in CD47 expression in cancer cells from the OE-MLKL C57BL/6 orthotopic model." (PMID 39025845, 2024). "A major mechanism by which cancer cells evade the innate immune system is the expression of CD47, which is a cell surface protein that interacts with signal regulatory protein α (SIRPα) on the surface of macrophages to block phagocytosis." (PMID 38183060, 2024). "In cancer, CD47 not only inhibits phagocytosis via SIRPα but also affects tumor growth and metastasis through integrin signaling and modulation of angiogenesis." (PMID 39039207, 2024). "Various treatment strategies, including the use of antibodies targeting CD47, RNA interference for CD47 silencing, and agents modulating CD47 expression, have demonstrated efficacy in cancer treatment by disrupting the interaction between CD47 and SIRPα." (PMID 38543240, 2024). "Prominent among immune evasion pathways in GBM and other cancers, CD47 provides a “don’t eat me” signal by binding SIRPα expressed on macrophages and microglia." (PMID 39545414, 2024). "For most types of cancers, the CD47/Sirpα immune checkpoint has attracted the most attention in immunotherapy." (PMID 38832992, 2024). "In this review, we highlight the difficulties in CD47/SIRPα targeted drug development for cancer immunotherapy, look into the future perspectives and explore potential solutions to improve CD47-SIRPα targeted drug development." (PMID 39040441, 2024). "Cancer cells can overexpress CD47, an innate immune checkpoint that prevents phagocytosis upon interaction with signal regulatory protein alpha (SIRPα) expressed in macrophages and other myeloid cells." (PMID 38414061, 2024). "The ligand of SIRPA is CD47, known as a “don’t eat me” signal, which is highly expressed on cancer cells compared to normal cells." (PMID 38920727, 2024). "CD47-SIRPα interaction is a biological process in which the protein CD47 on the surface of various cells, including cancer cells, interacts with SIRPα on the surface of macrophages." (PMID 38881902, 2024). "Many cancers evade attack by phagocytes through increasing CD47 expression, but it has been shown that the potent phagocytosis of low SIRPα-expressing macrophages when activated by pro-inflammatory factors is independent of CD47 expression." (PMID 40458305, 2024). "In physiological conditions, the SIRPα/CD47 pathway is involved in immunotolerance; however, in malignancy, it helps the cancer cells to achieve immune evasion." (PMID 36829496, 2023). "This inhibition of phagocytosis was not achieved by inhibiting the proliferative activity of macrophages as well as cancer cells A549, or the innate immunity CD47/SIRPα axis." (PMID 37259426, 2023). "For instance, CD47 is expressed on many cancer cells, and binding of CD47 to signal-regulatory protein α (SIRPα) on macrophages results in inhibition of macrophage phagocytic activity." (PMID 37723178, 2023). "Cancer cells express CD47 highly, which binds to SIRPα on phagocytes, leading to the evasion from immune surveillance." (PMID 36882399, 2023). "CD47 is known as a “don’t eat me signal” and binds to signal-regulatory protein alpha (SIRP-α) expressed on macrophages, allowing cancer cells to escape phagocytosis by macrophages." (PMID 36768216, 2023). "We were interested in SIRPα, MERTK and TREM2 because of their roles in the phagocytosis of cancer and apoptotic cells." (PMID 37483607, 2023). "Altogether, these results provide evidence for a shift in macrophage populations during the stepwise progression from normal tissue to cancer, accompanied by the upregulation of the CD47/SIRPα axis." (PMID 36442992, 2023). "In various cancers, CD47 acts as a self-signal to inhibit phagocytosis using interacting with the macrophage receptor SIRPα 11,18." (PMID 36860925, 2023).
cancer (continued). "SIRPα is expressed on TAMs and activated by CD47, an anti-phagocytic “don't eat me” surface protein expressed on cancer cells, particularly cancer stem cells." (PMID 37705736, 2023). "CD47 mAbs inhibit the interaction between CD47 and SIRPα and thereby activate TAM to phagocytose cancer cells." (PMID 36961012, 2023). "For example, by transfecting SIRPα plasmid DNA, SIRPα-expressed exosomes display an excellent affinity to CD47-naturally-overexpressed cancer HT29 cells." (PMID 37461033, 2023). "Along with the well-known PD-1, PD-L1, and CTLA-4, and in addition to SIRPα/CD47, TIM-3 has emerged as a promising target in cancer immunotherapy." (PMID 36829496, 2023). "The SIRPα/CD47 binding inhibits the antitumor immune response, which makes this a crucial druggable target in cancer immunotherapy." (PMID 36829496, 2023). "Recent progress has been made in targeting CD47 for cancer immunotherapy, and several CD47/SIRPα axis inhibitors have been developed for clinical trials with a favorable antitumor response in solid tumors and hematological malignancies." (PMID 36575242, 2023). "In general, SIRPα is considered as the most important ligand of CD47 and targeting CD47-SIRPα axis is regarded as a novel strategy in the treatment of cancer." (PMID 38125492, 2023). "Another macrophage marker that has demonstrated pre-clinical interest is the “do not eat me” signaling axis consisting of signal regulatory protein-alpha (SIRPα) expressed on the macrophage (and other phagocytes) and CD47 expressed on cancer cells." (PMID 36910138, 2023). "We validated the stepwise increase in the expression of these proteins from normal colorectal tissue to carcinoma (CD47, Spearman Rho=0.47, p=6.5×10−6; SIRPα, Spearman Rho=0.60, p=2.2×10−9)." (PMID 36442992, 2023). "As for SIRPα targeting strategy, it constantly fail to induce ADCP and ADCC against cancer cells when administrated alone due to immune cells target." (PMID 35557862, 2022). "Most cancer cells express CD47 on the surface; CD47 is known to bind to signal regulatory protein α (SIRPα)." (PMID 35989351, 2022). "Research on tri- or even tetra-specific antibodies has provided a conceptual breakthrough for a new cancer therapy, and studies of CD47/SIRPα-targeted tri- or tetra-specific antibodies for hematological malignancies are additionally required." (PMID 35978372, 2022). "Other immune checkpoints SIRPα and CD47 release a “don’t eat me” signal to prevent the recognization and phagocytosis of cancer cells by immune cells." (PMID 36300110, 2022). "Binding of BR105 to SIRPα blocks its interaction with CD47, thereby promoting macrophage phagocytosis of cancer cells." (PMID 35256517, 2022). "There are two emerging CD47-targeting strategies for cancer therapy, including interrupting the binding of CD47/SIRPα and downregulating CD47 expression at the transcriptional, translational, and post-translational levels." (PMID 36274066, 2022). "SIRPα is established as a myeloid inhibitory immunoreceptor, which can interact with CD47 on cancer cells and send ‘don't eat me’ signal to phagocytes." (PMID 35256517, 2022). "Twenty ICC and 20 paracancer tissue samples collected between July 1, 2016 and July 1, 2019 from The Affiliated Cancer Hospital of Zhengzhou University were tested for the expression of MMP19 and SIRPα." (PMID 36158683, 2022). "By targeting SIRPα, neutrophil-mediated ADCC of various opsonized cancer cells, such as breast cancer, neuroblastoma, and colorectal adenocarcinoma was promoted." (PMID 35884427, 2022). "By binding CD47 on cancer cells, DSP107 blocks the CD47/SIRPα cross talk, thereby inducing phagocytosis of cancer cells." (PMID 35978372, 2022). "Cancer cells can escape macrophage-mediated phagocytosis through expression of CD47, which interacts with SIRPα on the surface of macrophages to trigger the “don’t eat me” signal." (PMID 35229723, 2022).